UCA1 (urothelial cancer associated 1)
Diseases named in the same sentence as UCA1 in open-access papers (continued):
Sharing a sentence is not in itself a finding about the gene and the disease.
gastric cancer (continued). "For example, long non-coding RNA such as lncRNA UCA1 inhibits the apoptosis pathway and induces the resistance in gastric cancer cells to adriamycin and 5-fluorouracil functioning as a sponge of miR-27b to downregulate caspase-3 expression." (PMID 33842314, 2021). "Function analysis verified that UCA1 promoted cell proliferation and inhibited cell apoptosis in the gastric cancer cells in vitro and in vivo." (PMID 34238213, 2021). "In gastric cancer, UCA1 was aberrantly increased and promoted tumor metastasis by significantly induced ZEB2 expression through sponging miR-203." (PMID 33743811, 2021). "UCA1 expression was higher but miR-145 expression was lower in gastric cancer cell lines or tissues, compared to the adjacent normal cell line or normal tissues." (PMID 34238213, 2021). "For example, UCA1 promotes gastric cancer cell proliferation by activation of AKT via recruiting EZH2." (PMID 34809621, 2021). "For example, lncRNA UCA1 represses the host immune systems by upregulating the PD-L1 level of gastric cancer cells by reducing miRNAs expression." (PMID 33741027, 2021). "Western blot and quantitative real-time PCR (QPCR) were performed to test the expression level of the UCA1/miR-145/MYO6 axis in gastric cancer cell lines and tissues." (PMID 34238213, 2021). "The roles of the UCA1/miR-145/MYO6 axis in gastric cancer in vitro and in vivo were investigated by CCK-8 assay, flow cytometry, siRNAs, immunohistochemistry, and a mouse xenograft model." (PMID 34238213, 2021). "The lncRNA urothelial cancer associated 1 (UCA1) is highly expressed in multiple human cancers, including hepatocellular cancer, gastric cancer, colorectal cancer and lung cancer, which confers a worse overall patient survival 72-77." (PMID 32549757, 2020). "UCA1 (another lncRNA) expression is elevated in gastric cancer, and UCA1 can inhibit miR-214 expression and upregulate PDL1 expression, thus contributing to immune escape in gastric cancer cells." (PMID 33173530, 2020). "To date, several lncRNAs, including RMRP, AA174084, PVT1, H19, LINC00982, ABHD11-AS1 (ABHD11 antisense RNA 1), UCA1 (urothelial cancer associated 1), and LINC00152 have been identified from gastric juice and demonstrated as biomarkers for gastric cancer." (PMID 32460771, 2020). "UCA1 represses miR‐26a/b, miR‐193a, and miR‐214 expression through direct interaction in gastric cancer." (PMID 32767514, 2020). "UCA1 also increases the metastatic ability of gastric cancer cells, accelerates proliferation, increases cisplatin chemoresistance, and restrains apoptosis in oral squamous cell carcinoma cells." (PMID 32767514, 2020). "In gastric cancer, lncRNA UCA1 enhanced the translation of cyclin D1 via recruiting EZH2 and further precipitated the proliferation and cell cycle progression of gastric cancer." (PMID 32587476, 2020). "In gastric cancer, UCA1 has been shown as an early detection serum maker, and the induction of UCA1 by TGF-β leads to the enhanced invasion and migration in gastric cancer cells." (PMID 30940776, 2019). "Although UCA1 has been shown to play important biological roles in gastric cancer, the precise molecular mechanisms by which UCA1 modulates tumor progression needs to be clarified." (PMID 30464170, 2018). "LncRNA UCA1 binds to several microRNAs in different tumors (e.g., miR-216b in liver cancer, miR-204 in esophageal and colon cancer, miR-27b in gastric cancer) and influences entire transcriptional programs as well as response toward therapy." (PMID 29967761, 2018). "Silencing of lncRNA UCA1 in in vitro and in vivo systems proved the oncogenic role of lncRNA UCA1 in gastric cancer." (PMID 29967761, 2018). "UCA1 induces EMT in gastric cancer cells, and many molecules involved in EMT, such as transcription factors and miRNA, have been investigated." (PMID 30464170, 2018). "Bioinformatics analyses showed that UCA1 was highly expressed in tumor tissues from gastric cancer patients." (PMID 29212166, 2017).
gastric cancer (continued). "To identify the biological functions of UCA1 in gastric cancer, we selected the high expression BGC-823 cell line." (PMID 29212166, 2017). "The results showed that UCA1 expression was significantly upregulated in gastric cancer cell lines compared with the normal gastric epithelial cell line GES-1." (PMID 29212166, 2017). "Some recent studies reported that UCA1 is overexpressed and has an oncogenic function in various cancers, such as hepatocellular carcinoma, breast cancer, colorectal cancer and gastric cancer." (PMID 29221199, 2017). "UCA1 silencing significantly inhibited gastric cancer BGC-823 cell proliferation and increased its apoptosis." (PMID 29212166, 2017). "Taken together, the results showed that silencing of UCA1 inhibited gastric cancer tumorigenesis progression in vivo." (PMID 29212166, 2017). "Aberrant over-expression of UCA1 has been found in melanoma, ovarian cancer, gastric cancer and other malignancies." (PMID 28209917, 2017). "We showed that UCA1 expression was significantly upregulated in gastric cancer tissues and cell lines, and the upregulated UCA1 correlated with the gastric cancer TNM stage and lymph node metastases." (PMID 29212166, 2017). "Taken together, the results showed that UCA1 silencing inhibited cell migration and invasion in gastric cancer cells." (PMID 29212166, 2017). "Particularly, UCA1 was found to be a significant prognostic indicator of DFS for patients with gastric cancer (HR =2.54; 95 % CI = 1.09–4.00, p= 0.001)." (PMID 28380443, 2017). "Integrated analyses showed that UCA1 expression was frequently higher in gastric cancer tissues and gastric cancer cells." (PMID 29212166, 2017). "UCA1 has also been shown to regulate EMT in Gastric Cancer as, silencing of UCA1 resulted in decreased levels of vimentin and snail, with concomitant elevated levels of E-cadherin." (PMID 28430163, 2017). "Previous studies demonstrated that lncRNA UCA1 played important roles in the development of tumors such as renal cell carcinoma, gastric cancer, colon cancer, hepatocellular carcinoma and osteosarcoma." (PMID 29207643, 2017). "We also found that UCA1 played an important role in the migration and invasion of gastric cancer cells in vitro and in vivo." (PMID 29212166, 2017). "Together, the resulted showed that UCA1 affected malignant progression of gastric cancer cells partly through p-AKT3 and p-mTOR in the PI3K-Akt-mTOR signaling pathway." (PMID 29212166, 2017). "According to our previous study, some of the gastric cancer-related mRNAs were co-expressed with UCA1 and were involved in the PI3K-Akt-mTOR signaling pathway." (PMID 29212166, 2017). "A wound healing assay and the Transwell® invasion assay were used to detect gastric cancer cell migration and invasion capability using UCA1 gene overexpression and interference techniques." (PMID 29212166, 2017). "As a proof of the functional importance of lncRNA, we showed that gastric cancer development and progression were potentially regulated by UCA1 expression." (PMID 29212166, 2017). "For gastric cancer, a combination of UCA1/CUDR, LSINCT-5, and PTENP1 was reported to be of diagnostic value." (PMID 29147109, 2017). "Taken together, the results helped to identify the function of UCA1 and its role in gastric cancer tumorigenesis." (PMID 29212166, 2017). "Expression of UCA1 was negatively correlated with the miR-27b and the UCA1-miR-27b axis was involved in regulation of chemo-sensitivity of gastric cancer cells." (PMID 28380443, 2017). "Based upon these results, we suggest that UCA1 can be a novel target for therapeutic intervention of gastric cancer." (PMID 29212166, 2017). "In the subgroup analyses, UCA1 levels were significantly and negatively associated with OS times in colorectal cancer, NSCLC, ovarian cancer, and gastric cancer." (PMID 27329842, 2016).
gastric cancer (continued). "Similarly, the increased expression of lncRNA UCA1 has been shown to promote the invasion and metastasis of gastric cancer cells by acting as a sponge for miR-145, thereby influencing the expression of MYO6." (PMID 40299524, 2025). "Conversely, knockout of UCA1 results in reduced migration of gastric cancer cells." (PMID 39690423, 2024). "Likewise, a serum three-lncRNA signature consisting of PTENP1, LSINCT-5 and CUDR (also known as UCA1) significantly outperformed CEA and CA19-9 in gastric cancer diagnostic studies." (PMID 35729321, 2022). "Knockout of UCA1 increases drug sensitivity of various cancers, including gastric cancer." (PMID 35402492, 2022). "It was also observed that aberrant expression of UCA1 facilitated to immune escape of gastric cancer, which was consistent with our findings that UCA1 might be involved in the immune response of cancer." (PMID 34285140, 2021). "Another report pointed out that UCA1 elevated doxorubicin resistance in gastric cancer." (PMID 33969374, 2021). "In the present study, we aimed to identify how UCA1 promotes gastric cancer development." (PMID 34238213, 2021). "Additionally, overexpression of UCA1 was demonstrated to promote the migration, invasion, and metastasis of gastric cancer cells." (PMID 33520725, 2020). "The relationship between UCA1-expression level and clinical-pathological features of 60 paired gastric cancer samples and adjacent normal tissues showed that UCA1 upregulation was closely associated with lymph node metastasis and patient age but not tumor position or patient gender." (PMID 30464170, 2018). "LncRNA UCA1 was up-regulated in esophageal squamous cell carcinoma, gastric cancer tissues and cell lines, knockdown of UCA1 could inhibit proliferation of cancer cells." (PMID 29568404, 2018). "In addition, UCA1 was shown to stimulate the ERK-MMP9 signaling in gastric cancer cells by interacting with G protein-coupled receptor kinase 2 (GRK2), stimulating its ubiquitination and degradation." (PMID 30441811, 2018). "For example, TGFβ1-induced LncRNA UCA1 upregulation promotes gastric cancer invasion and migration." (PMID 30250403, 2018). "We also found that UCA1-expression levels correlated with tumor stage IV in gastric cancer samples." (PMID 30464170, 2018). "Knockdown of UCA1 increases the sensitivity to tamoxifen in breast cancer through inhibition of Wnt/β-catenin pathway, and also promotes chemotherapy sensitivity to adriamycin in gastric cancer and accelerates cellular apoptosis pathway." (PMID 29416703, 2018). "It has been reported that ecCEBPA levels are upregulated in gastric cancer tissues compare to noncancer ones, suggesting that, as consequence, also CEBPA gene transcription increases; indeed, one of the CEBPA target genes, the lncRNA UCA1, is upregulated in gastric cancer tissues." (PMID 29443889, 2018). "However, epigenetic mechanisms of UCA1 that regulate the metastasis process during gastric cancer have rarely been reported." (PMID 30464170, 2018). "The exact molecular mechanism behind the differential expression of MEG3 and UCA1 could be due to ethnic difference and the etiological factors specific to Indian gastric cancer patients." (PMID 29719612, 2018). "Collectively, the results showed a pivotal role of UCA1 in the tumorigenesis of gastric cancer." (PMID 29212166, 2017). "In conclusion, the present study helped to define the role of UCA1 in gastric cancer tumorigenesis." (PMID 29212166, 2017). "Together, the results suggested that UCA1 may function as an oncogene in gastric cancer progression." (PMID 29212166, 2017). "We also characterized the effects of UCA1 on the PI3K-Akt-mTOR signaling pathway in gastric cancer." (PMID 29212166, 2017). "Similarly, the increased expression of the lncRNA UCA1 also predicted the shorter DFS in patients with gastric cancer or HCC." (PMID 28410241, 2017). "Together, our results showed that silencing of UCA1 inhibited gastric cancer tumor growth in vivo." (PMID 29212166, 2017).
gastric cancer (continued). "For gastric cancer, UCA1 was observed to be highly expressed, while the silence of UCA1 could decrease proliferation of tumor cells." (PMID 28380443, 2017). "In a manner similar to that observed for HOTAIR, UCA1 has also been shown to regulate miRNAs (in this instance miR-27b) as part of a multi-drug resistance to various chemotherapies (including cisplatin) in gastric cancer." (PMID 28430163, 2017). "Furthermore, a functional assay indicated that UCA1 silencing significantly inhibited gastric cancer BGC-823 cell proliferation and increased apoptosis." (PMID 29212166, 2017). "For UCA1, pieces of evidence also documented that ectopic expression of UCA1 boosted cell migration and invasion via activating the vimentin and snail expression, and suppressed E-cadherin and zonula occludens-1 protein levels in gastric cancer." (PMID 29221199, 2017). "We also showed that UCA1 might play an important role in the migration and invasion of gastric cancer cells in vitro and in vivo." (PMID 29212166, 2017). "We also determined whether UCA1 played an important role in migration and invasion of gastric cancer." (PMID 29212166, 2017). "Together, these results showed the in vitro effects of UCA1 on gastric cancer cell proliferation and apoptosis; however, the relationship between the expression of UCA1 and gastric cancer progression still remains unclear." (PMID 29212166, 2017). "UCA1 is therefore a potential oncogene that may play an important regulatory role in the clinical progression of gastric cancer." (PMID 29212166, 2017). "In addition, based on the UCA1 expression of gastric cancer cells, we constructed overexpression systems and used silencing lentivirus vectors to investigate the biological function of UCA1 in vitro and in vivo." (PMID 29212166, 2017). "However, function and underlying mechanism of UCA1 in the progression of gastric cancer (GC) remain unclear." (PMID 28569779, 2017). "As it was observed that UCA1 is up-regulated in liver, colon and stomach cancers, it may be a biomarker for the diagnosis of these cancers." (PMID 26160838, 2015). "Upregulated UCA1 expression was observed in patients with gastric cancer and suggested that its upregulation could regulate the spread of gastric cancer cells and metastases and significantly associated with lymph node metastases and the TNM stage could be the biomarker of malignancy." (PMID 35132340, 2022). "However, the underlying mechanism of UCA1 in the development of gastric cancer is not fully understood." (PMID 34238213, 2021). "miR-145 mimics or MYO6 siRNAs could partly reverse the effect of UCA1 on gastric cancer cells." (PMID 34238213, 2021). "Besides, there are very limited studies on the involvement of lncRNA UCA1 in tumor immunity, among which studies found that lncRNA UCA1 as an oncogene could suppress the host immune system by up-regulating the PDL1 level in gastric cancer cells (Wang J.-D." (PMID 34777462, 2021). "It has been reported that lncRNA UCA1 stimulates cell proliferation, migration, immune escape, and apoptosis inhibition in gastric cancer (GC) by acting as a ceRNA for antitumor miRNAs." (PMID 32878637, 2020). "UCA1 is a long non-coding RNA which was found overexpressed in various human cancers including gastric cancer (GC)." (PMID 31272462, 2019). "As an lncRNA, although UCA1 was found overexpressed in gastric cancer, the role of UCA1 in GC is still not fully understood." (PMID 31272462, 2019). "Zuo uncovered that the elevation of UCA1 is correlated with the LNM of gastric cancer (GC); besides, UCA1 regulates the EMT of GC cells possibly through transforming growth factor-β1 (TGFβ1) induction in vitro." (PMID 29368602, 2018). "We then tested whether UCA1 promotes gastric-cancer metastasis in a miR-203/ZEB2-dependent manner." (PMID 30464170, 2018). "In addition, metastasis studies of UCA1 during gastric cancer have rarely been reported." (PMID 29212166, 2017).
gastric cancer (continued). "Therefore we determined whether UCA1 played an important role in migration and invasion of gastric cancer cells in vitro." (PMID 29212166, 2017). "In previous studies, we used microarray analyses to screen differential expression profiles of lncRNAs from advanced gastric cancer tissues and adjacent non-tumor tissues, to show significantly higher expression of the lncRNA urothelial carcinoma-associated 1 (UCA1)." (PMID 29212166, 2017). "However, the biological role and potential regulation mechanism of UCA1 in the carcinogenesis of gastric cancer remain unclear." (PMID 29212166, 2017). "Furthermore, our previous studies using microarray screening and bioinformatics analyses to construct the lncRNA-mRNA co-expression network, showed that some of the gastric cancer-related mRNAs were co-expressed with UCA1 and were involved in the regulation of the PI3K-Akt-mTOR signaling pathway." (PMID 29212166, 2017). "Serum-derived UCA1, PCGEM1, and CUDR are potential new biomarkers for the early detection of gastric cancer, as confirmed by qRT‒PCR and other techniques 174-176." (PMID 38706913, 2024). "For gastrointestinal cancer, the prognostic value of CEBPA-DT was illustrated along with several other lncRNAs (INHBA-AS1, AK001058, UCA1, PPBP, and RGS18) in early gastric cancer." (PMID 36471363, 2022). "UCA1 down-regulates gene CREB1 expression by sponging microRNA miRNA-590-3p, promoting cells proliferation and invasion of gastric cancer, thus acting as an oncogene." (PMID 35402492, 2022). "The Cancer Genome Atlas (TCGA) and Genotype-Tissue Expression (GTEx) data were used to analyze UCA1 and myosin VI (MYO6) expression in gastric cancer." (PMID 34238213, 2021). "For instance, lncRNA UCA1 mediates the expression of p21 and SPRY1 through interacting with EZH2, thus facilitating tumour progression of gastric cancer." (PMID 33834618, 2021). "Multiple onco-lncRNAs, such as HOTAIR, CASC9, MRUL, UCA1, D63785, NEAT1 and HULC, are involved in ADR resistance in gastric cancer." (PMID 32192494, 2020). "UCA1 overexpression had been shown to protect PDL1 expression from the repression of miRNAs and contributed to the gastric cancer cells immune escape." (PMID 32127004, 2020). "It has further been shown that silencing UCA1 increases the expression level of caspase-3, thus promoting apoptosis and reversing MDR in gastric cancer cells in vitro." (PMID 32460771, 2020). "In contrast, another mechanism reported for miR-203 regulation is sponging via the competing endogenous RNA (ceRNA) long non-coding RNA (lncRNA) UCA1, which resulted in an upregulated ZEB2-mediated EMT pathway in gastric carcinoma." (PMID 32708601, 2020). "However, little is known about the exact role and regulation mechanism of lncRNA UCA1 during the progression of gastric cancer (GC)." (PMID 30464170, 2018). "UCA1 has been reported to be upregulated in gastric cancer (GC); however, the underlying functional roles of UCA1 in GC have not been established." (PMID 29516678, 2018). "Taken together, the results showed that UCA1 silencing inhibited BGC-823 cell migration and invasion, suggesting that UCA1 can be used as a gene-specific target for gastric cancer treatment." (PMID 29212166, 2017). "The study of the molecular mechanism of UCA1 suggested that UCA1 regulates PI3K-Akt-mTOR signaling proteins and their downstream mediators, and alters gastric cancer progression in vitro and in vivo." (PMID 29212166, 2017). "The most significantly upregulated gastric cancer cell line was BGC-823, with a 30.810-fold change of UCA1 when compared with that of the GES-1 cells (P < 0.01)." (PMID 29212166, 2017). "The MTT cell proliferation assay and flow cytometry both suggested that lentivirus-UCA1-siRNA stably-transfected BGC-823 cells showed significantly decreased proliferation and increased cell apoptosis of gastric cancer BGC-823 cells." (PMID 29212166, 2017).